NRARP (NOTCH regulated ankyrin repeat protein)
Description:
Downstream effector of Notch signaling. Involved in the regulation of liver cancer cells self-renewal. Involved in angiogenesis acting downstream of Notch at branch points to regulate vascular density. Proposed to integrate endothelial Notch and Wnt signaling to control stalk cell proliferation and to stablilize new endothelial connections during angiogenesis. During somitogenesis involved in maintenance of proper somite segmentation and proper numbers of somites and vertebrae. Required for proper anterior-posterior somite patterning. Proposed to function in a negative feedback loop to destabilize Notch 1 intracellular domain (NICD) and down-regulate the Notch signal, preventing expansion of the Notch signal into the anterior somite domain (By similarity).
Synonyms: MGC61598
Tractability: No criterion of Open Targets' tractability assessment is met for any kind of drug.
Gene: Protein-coding gene on chromosome 9 (137,299,631 to 137,302,271, reverse strand). Ensembl gene ENSG00000198435.
Subcellular location (Human Protein Atlas): Cytosol; Nucleoplasm
Gene Ontology:
Molecular function: protein binding
Biological process: negative regulation of Notch signaling pathway; Notch signaling pathway; positive regulation of canonical Wnt signaling pathway; blood vessel endothelial cell proliferation involved in sprouting angiogenesis; branching involved in blood vessel morphogenesis
Genetic constraint (gnomAD): Loss-of-function variants: 1 observed, 1.85 expected, observed/expected ratio (o/e) 0.54, 90% interval 0.18 to 1.77. That is too few expected variants to judge how well the gene tolerates losing a copy. Missense variants: 83 observed, 142.68 expected, observed/expected ratio (o/e) 0.58, 90% interval 0.49 to 0.7. Synonymous variants: 81 observed, 67.76 expected, observed/expected ratio (o/e) 1.2, 90% interval 1 to 1.44.
Homologues: Orthologues: chimpanzee NRARP (100% identical), macaque NRARP (100% identical), mouse Nrarp (100% identical), rat Nrarp (100% identical), dog NRARP (98% identical), pig NRARP (98% identical), tropical clawed frog nrarp (92% identical), zebrafish nrarpa (89% identical), zebrafish nrarpb (85% identical). Paralogues in human: ANKRD6 (35% identical), ANKRD10 (25% identical).
Diseases named in the same sentence as NRARP in open-access papers:
NRARP is named in the same sentence as 18 diseases in open-access papers, as found by Europe PMC text mining. Sharing a sentence is not in itself a finding about the gene and the disease. The quoted sentences say what the papers report.
breast carcinoma (3 papers, 2021 to 2024). "Notch-regulated ankyrin repeat protein (NRARP) is a key regulator in both Notch and Wnt signaling pathways that are essential for breast cancer proliferation." (PMID 34629100, 2021).
colon cancer (2 papers, 2017 to 2021). "Besides, the recent study which revealed that increased NRARP is involved in NOTCH-induced EMT in colon cancer also enhanced the functional association between NRARP and EMT." (PMID 28207739, 2017).
T-cell acute lymphoblastic leukemia (2 papers, 2020). Acute lymphoblastic leukemia of T-cell origin. "Only a few genes, such as HES4, HEY1, MYC, NOTCH3, NRARP, and TFRC, are similarly regulated in mutationally activated NOTCH1-driven cancers, such as T-cell acute lymphoblastic leukemia (T-ALL), mantle cell lymphoma (MCL), and breast cancer." (PMID 33003595, 2020).
breast tumor (1 paper, 2017). "Noteworthy, NRARP silencing can reduce the breast tumor proliferation, which proves NRARP itself can work as a driver oncogene instead of a passenger, of which over-activation promotes tumor cell growth or survival." (PMID 28207739, 2017).
hepatocellular carcinoma (1 paper, 2018). A malignant tumor that arises from hepatocytes. "In human hepatocellular carcinoma, Notch2 regulates the stemness of liver CSCs via upregulation of NRARP, HES1 and HES6." (PMID 30285832, 2018).
leukemia (1 paper, 2020). A malignant (clonal) hematologic disorder, involving hematopoietic stem cells and characterized by the presence of primitive or atypical myeloid or lymphoid cells in the bone marrow and the blood. "As expected, mice transplanted with NICD1-expressing D1 cells developed leukemia rapidly, whereas mice transferred with D1 cells co-expressing NICD1 and NRARP developed leukemia significantly later." (PMID 31586130, 2020). "By contrast, mice transplanted with D1 cells overexpressing NRARP alone developed leukemia with similar kinetics to those transplanted with D1 NICD1 cells, confirming the oncogenic potential of NRARP in the context of low levels of Notch1 signaling." (PMID 31586130, 2020). "Consistent with this hypothesis, mice transplanted with T-cells co-expressing NOTCH1 and NRARP develop leukemia later than mice transplanted with T-NOTCH1 cells." (PMID 31586130, 2020). "Importantly, mice transplanted with T-cells overexpressing NRARP alone developed leukemia with similar kinetics to those transplanted with T-NOTCH1 cells." (PMID 31586130, 2020). "With the exception of DND4.1 cells, we did not observe significant differences in leukemia cell viability upon NRARP overexpression." (PMID 31586130, 2020).
liver cancer (1 paper, 2017). An epithelial or non-epithelial malignant neoplasm that arises from the liver. "As the downstream effector of Notch signaling, NOTCH-Regulated Ankyrin Repeat Protein (NRARP) that can be activated by NOTCH pathway was previously reported to be over-expressed in some cancers like breast cancer and liver cancer." (PMID 28207739, 2017).
medulloblastoma (1 paper, 2018). A malignant, invasive embryonal neoplasm arising from the cerebellum. "In medulloblastoma DAOY cells, as well as in MCF7 cells, expression of cytoplasmic NERT2 did not enhance HIF2α or NRARP expression, whereas tamoxifen-induced nuclear localization of NERT2 for 8 h led to a robust upregulation of HIF2α and NRARP expression." (PMID 29993038, 2018).
thyroid (1 paper, 2017). "Since NRARP participates in thyroid malignancies development and correlates with poor survival, our analysis provides a novel insight into the prognostic marker for thyroid cancer." (PMID 28207739, 2017).
thyroid cancer (1 paper, 2017). "The results demonstrated that NRARP expression is a predictive biomarker for the outcome of the thyroid cancer." (PMID 28207739, 2017). "Here we reveal that NRARP can coordinate with NOTCH genes to regulate thyroid cancer aggression and to stimulate EMT." (PMID 28207739, 2017). "To understand the molecular mechanisms of NRARP involved in thyroid cancer progression, we further detected the linkage between EMT and NRARP." (PMID 28207739, 2017). "In conclusion, our work establishes a strong linkage between NRARP and thyroid carcinoma progression." (PMID 28207739, 2017). "The similar expression pattern implied that NRARP is frequently activated in mRNA level and may play an oncogenic role in thyroid cancer." (PMID 28207739, 2017). "NRARP is frequently over-expressed in thyroid cancer whose activation may contribute to EMT depending on activated NOTCH signaling pathways." (PMID 28207739, 2017). "NRARP dysregulation can contribute to aggression and lethality of the thyroid cancer." (PMID 28207739, 2017). "These experiments at least partially support our findings that NRARP plays a direct oncogenic role in connecting NOTCH signals to thyroid cancer progression and disprove it is only the ‘random product’ of cancer development and carry no functional significance." (PMID 28207739, 2017). "In this study, we show that NRARP is frequently over-expressed in thyroid carcinoma." (PMID 28207739, 2017). "NRARP and some other genes involved in NOTCH pathways are all over-expressed in thyroid cancer." (PMID 28207739, 2017).
thyroid tumor (1 paper, 2017). A benign or malignant neoplasm affecting the thyroid gland. "Together, these observations all support our hypothesis that NRARP works as the oncogene contributing the thyroid tumor aggression." (PMID 28207739, 2017). "We have identified NRARP as an oncogene candidate over-expressed in THCA and its over-activation can contribute to thyroid tumor aggression by correlating with NOTCH, but the mechanisms are less clear." (PMID 28207739, 2017).
tumor (6 papers, 2015 to 2023). "We next queried whether NOTCH1 signalling was dysregulated within tumour cells, especially given the genomic disruption in each tumour of one allele of NRARP, the negative regulator of NOTCH1." (PMID 37749094, 2023). "On one hand, NRARP has a ‘tumor suppressor’-like role in T-ALL cells with high levels of NICD by inhibiting Notch1 signaling." (PMID 31586130, 2020). "As expected, NRARP, a Notch related mediator and downstream is also up-regulated in tumor patients when compared with the normal samples." (PMID 28207739, 2017). "To investigate the NRARP functions of tumorigenesis in tumor, we further performed a correlation analysis in TCGA tumor samples." (PMID 28207739, 2017). "Expectedly, C8orf4-deficient tumours showed elevated expression levels of NOTCH2 target genes such as HEY1, HES6 and NRARP." (PMID 25985737, 2015). "Consistently, high expression levels of HEY1, HES6 and NRARP in HCC tumours were validated by Zhang's cohort (GSE25097)." (PMID 25985737, 2015). "Besides, NRARP expression is also positively correlated with such NOTCH related genes across the tumor patients by excluding normal samples." (PMID 28207739, 2017). "NRARP knockdown also attenuated tumour-initiating capacity and liver CSC ratios." (PMID 25985737, 2015). "We observed that HEY1, HES6 and NRARP were highly expressed in the tumour tissues of HCC patients." (PMID 25985737, 2015). "The expression consistency of NRARP and NOTCH genes occurring not only within the tumor patients also between the tumors and normals indicated a strong regulation relationship in PTCs." (PMID 28207739, 2017). "Moreover, the expression levels of NRARP, HEY1 and HES6 in tumours are positively correlated with clinical severity and prognosis of HCC patients." (PMID 25985737, 2015). "In addition, depletion of NRARP and HEY1 impairs the stemness maintenance of liver CSCs and tumour propagation." (PMID 25985737, 2015).
cancer (4 papers, 2010 to 2021). A tumor composed of atypical neoplastic, often pleomorphic cells that invade other tissues. "NOTCH signaling and its downstream NOTCH-Regulated Ankyrin Repeat Protein (NRARP) have been implicated in oncogenesis of many cancers, but the roles in PTCs are less studied." (PMID 28207739, 2017). "NRARP, which stands for Notch-regulated ankyrin repeat protein, acts downstream of Notch signaling, and functions in cancer progression, cancer stem cell self-renewal, angiogenesis, as well as in patterning, and development." (PMID 31740700, 2019). "The experiment by Zhu Zusen group proved that NRARP knockout led to attenuate cancer cell stemness which is linked with EMT by TWIST1 and ZEB1, two EMT related transcription factors that are also highly correlated with NRARP." (PMID 28207739, 2017). "NRARP is increased by NOTCH signaling and in turn regulate NOTCH signaling as well as cooperate with it to induce cancer EMT and cancer stemness." (PMID 28207739, 2017). "Our correlation analysis and literature mining suggested that NRARP promotes EMT and cancer invasion via NOTCH signaling activation." (PMID 28207739, 2017). "Notch1 signaling is increased in a variety of cancers and activates downstream target genes, including HES1, HES5, DTX1, NRARP, and c-MYC." (PMID 20161710, 2010). "In this study, we hypothesize that NRARP is activated in PTC and induces the cancer progression." (PMID 28207739, 2017). "Thus, PODXL and NRARP may be conserved SALL2 targets across species, tissues, and cancer types." (PMID 33692826, 2021).
respiratory diseases (1 paper, 2022). "Although the significance between the NRARP gene and respiratory diseases was not analyzed in the network analyses of our study, respiratory effects and cell cycle regulation-related carcinogenic effects of NRARP would be valuable in future formaldehyde studies." (PMID 35379891, 2022).
NRARP also shares sentences with these, for which no sentence is quoted: aortic aneurysm (1 paper); lung carcinoma (1); mantle cell lymphoma (1); melanoma (1).